LAG3 (lymphocyte activating 3)
Diseases named in the same sentence as LAG3 in open-access papers (continued):
Sharing a sentence is not in itself a finding about the gene and the disease.
tumor (continued). "Murine models indicate that combined blockade of the PD-1 axis and LAG-3 enhances rejection of multiple tumor types, even when single agent blockade of anti-PD-1 therapy was ineffective." (PMID 34068762, 2021). "Because there was only one LAG3-positive-expressing tumor, we combined the positive tumor with the low-expressing tumors into the positive group for LAG3 analysis." (PMID 34072549, 2021). "It has been demonstrated that LAG-3 KO CAR-T cells displayed robust anti-tumor activity in the murine xenograft model." (PMID 34830003, 2021). "In this study, we assessed the ability of this single-domain antibody to image LAG-3 on tumor-infiltrating lymphocytes (TILs) in different mouse cancer models by SPECT/CT." (PMID 33712537, 2021). "Tumor samples of patients with PD-L1+ cells exhibited the increased levels of both PD-1 and LAG-3 expressions in tumor-infiltrating lymphocytes." (PMID 34081621, 2021). "The authors noted that intra-tumoral T cells in mice with higher tumor burden showed an exhausted phenotype with increased PD-1+ Lag-3+ and PD-1+ Tim-3+ CD8 T cells." (PMID 33708214, 2021). "The co-expression of LAG-3 and PD-1 has been observed on intratumoural T-cells in a subset of mouse xenograft tumours and human RCCs34–36." (PMID 34545095, 2021). "Included in this list is the co‐inhibitory receptor lymphocyte activation gene‐3 (LAG‐3), which is upregulated on T cells extracted from tumor sites that have suppressive or exhausted phenotypes." (PMID 32920841, 2021). "In conclusion, our results indicated that Tim-3 and Lag-3 as well as PD-1 axis suppress the immune response in the tumor microenvironment of GC." (PMID 33611641, 2021). "Many mAbs target LAG3, most of which are undergoing clinical trials, including IMP321(first LAG3 fusion protein) and relatlimab (first LAG3 mAb), and show good potential in tumor immunotherapy." (PMID 35111155, 2021). "GSK-3β negatively regulates the cell surface expression of LAG-3 on tumor infiltrating T lymphocytes." (PMID 34356465, 2021). "A good correlation was present between LAG3 levels and the tumour’s T lymphocyte fraction (R = 0.553, p < 0.001)." (PMID 34503258, 2021). "PD-1/PD-L1 and CD8 T cells are closely related, as PD-1 blockade can increase CD8 T cell and tumor-specific interferon-γ production in the tumor microenvironment or produce anti-tumor effects by increasing KLRG1 + LAG3 - TNFα+ tumor-specific T cells in tumors." (PMID 34439378, 2021). "An initial T cell‐mediated tumor arrest is later followed by a tumor escape, which correlates with the upregulation of the checkpoint molecules programmed cell death‐1 (PD‐1) and lymphocyte‐activation gene 3 (LAG3) on T cells." (PMID 33552509, 2021). "To our knowledge, we were the first to report different single-domain antibodies targeting mouse LAG-3 and to select one of these single-domain antibodies for detection of LAG-3–engineered tumor cells." (PMID 33712537, 2021). "As a control for the used mRNA/RNAseq expression levels, we analysed a second set of 15 UM from Leiden by Fluidigm qPCR, and compared the expression of LAG3, HLA-DR, and Galectin-3 between D3 vs. M3 tumours." (PMID 34503258, 2021). "Interestingly, also other immunosuppressive molecules like TIM3 or LAG3 were found to be significantly increased in tumor-associated antigen specific HCC infiltrating CD8+ lymphocytes and may represent valuable targets for novel therapeutic approaches alone or in combination." (PMID 33805268, 2021). "In the MC38 and CT26 colorectal cancer tumor mouse model, FS118 (bispecific antibody blocking PD-L1 and LAG3) showed a favorable anti-tumor effect by restoring the activation of T cells and was well tolerated without any toxicity." (PMID 35111155, 2021). "Accordingly, we also observed an increase in inhibitory checkpoints that can be expressed in both NK and T cells such as LAG-3 and suppressors of anti-tumor immunity such as IDO1." (PMID 34880879, 2021).
tumor (continued). "LAG-3 expression has also been described in exhausted CD8 PD1+ tumor-infiltrating lymphocytes (TILs)." (PMID 34067904, 2021). "In human GBM samples, LAG-3 is expressed on tumor-infiltrating immune cells, particularly in up to 30% of CD8+ T cells, and it is a marker of T-cell exhaustion." (PMID 34359588, 2021). "After tumor antigen stimulation, the level of LAG-3 expression in lymphocytes increases substantially." (PMID 34869005, 2021). "B16-F10 model mice treated with LAG-3-blockading antibody (monotherapy) only exhibited delayed tumor growth, whereas combination therapy targeting both LAG-3 and PD-1 at the time of relapse resulted in significant tumor regression." (PMID 34572799, 2021). "We assessed the accuracy of the radiolabeled single-domain antibodies to image LAG-3 expression levels in the tumor by comparing ex vivo γ-counts with the activity that can be measured on SPECT/CT scans using AMIDE software." (PMID 33712537, 2021). "Monotherapy of anti-PD-1 mAb, anti-PD-L1 mAb, anti-Tim-3 mAb, and anti-Lag-3 mAb led to a significantly higher cytotoxicity of tumor antigen specific CTL clones against GC cells as compared to no treatment control." (PMID 33611641, 2021). "Novel ICBs such as anti-TIM-3, anti-TIGIT, or anti-LAG-3 were also shown to restore the function of tumor-infiltrating T cells in vitro, and they are now under the early stage of clinical trials." (PMID 34575463, 2021). "Combined PD-1/LAG-3 blockade further delayed tumor growth when compared with IC mAbs (P = 0.0001) or monotherapy with anti-LAG-3 (P = 0.0201) or anti-PD-1 (P = 0.5257) mAbs." (PMID 33712537, 2021). "Upregulation of LAG-3 by tumour-specific CD4+ and CD8+ T cells in Tregs infiltrating PCa lesions has been observed." (PMID 33921181, 2021). "Tumor-mediated Gal-1 and Gal-3 have also been identified as inhibiting T cell cytotoxicity by interacting with the T cell receptor or lymphocyte activation gene 3 (LAG-3) and inducing T cell apoptosis." (PMID 34572346, 2021). "When looking at the percentages of positive cells we clearly saw that more CD8+ effector T cells that express PD-L1 and LAG-3 were found in the tumor compared to the spleen." (PMID 33466653, 2021). "Subsequently, we performed ROC curves to identify the efficacy of serum LAG-3 and PD-L1 for predicting tumor response." (PMID 34691076, 2021). "Fibrinogen-like protein 1 (FGL1) is a new major ligand for LAG-3 and it has recently been demonstrated that blocking the FGL1-LAG-3 pathways results in the stimulation of tumour immunity and inhibits tumour growth." (PMID 33995362, 2021). "LAG3 expression widely suppresses anti-tumor immunity directly by impairing T/NK cells, and indirectly through impeding CD4+ T-cell functions via binding to MHC class II (MHC II) with a higher affinity than CD4." (PMID 33535613, 2021). "Compared to tumor-bearing mice, the expression of programmed cell death protein-1 (PD-1) and lymphocyte-activation gene 3 (Lag-3) on Tregs was clearly downregulated after RFA." (PMID 34576115, 2021). "Dual antibody blockade of LAG3 and PD-1 has been shown to significantly improve T-cell effector function and delay tumour growth in vivo in OC murine models." (PMID 34944851, 2021). "The same study also demonstrated that LAG-3 correlated strongly with PD-L1 and CD8 expression and also showed association with high tumor mutation burden and viral expression and, in particular EBV, across all tumors." (PMID 34068762, 2021). "This study demonstrated the central role LAG-3 plays in galectin-3-mediated suppression of lymphocyte anti-tumor effector function." (PMID 34572756, 2021). "Inhibitory checkpoints like programmed cell death protein‐1 (PD‐1), T‐cell immunoglobulin mucin‐domain containing‐3 (TIM‐3), and lymphocyte‐activation gene 3 (LAG‐3), are all present on T‐cells and all bind to ligands that are secreted by tumour cells." (PMID 33338327, 2021).
tumor (continued). "Tumors with B7-H3 expression also had the increased expression levels of both PD-1 and LAG-3 in tumor-infiltrating lymphocytes, and had higher density of CD8+ T cells than those without B7-H3 expression." (PMID 34081621, 2021). "The LAG3–MHCII bond has an inhibitory effect on the immunologic components of the tumor microenvironment." (PMID 34207243, 2021). "LAG-3 single-domain antibody tumor uptake in mice treated with anti-PD-1 or IC mAbs was also compared with the MFI of LAG-3 expression on TILs, measured in flow cytometry." (PMID 33712537, 2021). "LAG-3, another novel checkpoint, is expressed on effector T cells, Tregs, and DCs, and the evidence indicates that the upregulation of both PD-1 and LAG-3 leads to T cell exhaustion and tolerance to tumor antigens." (PMID 33801815, 2021). "As expected, not only did treatment with IL‐12 result in enhanced anti‐tumor response as seen by the suppression of tumor escape, it also resulted in the suppression of PD‐1 and LAG3 upregulation, providing further credentialing of the X‐mouse model." (PMID 33552509, 2021). "CD8+ T cells, the function of inflammation-promoting, high immune score, activation of TIM3, LAG3, and PD-L1 played vital roles in the hot tumor." (PMID 34790235, 2021). "Inhibitory receptor-mediated immune tolerance of HD cells is further reinforced by the co-localization of LAG3+ Treg near MHC class II-negative tumor cells by multicolor immunohistochemistry." (PMID 33732232, 2021). "Current study has displayed that FGL1 is the considerable ligand of the LAG-3 and FGL1-LAG-3 pathway contributes to tumor growth." (PMID 33867830, 2021). "Given that upregulation of LAG3 has been found in tumor-infiltrating CD8+ T cells and HCC cells, potential clinical trials for HCC can be expected in the near future." (PMID 34771459, 2021). "Co-expression of PD-1 and Lymphocyte activation gene-3 (Lag-3), or PD-1 and T cell immunoglobulin-3 (Tim-3) facilitated T cell exhaustion and led to tumoral immune escape." (PMID 33611641, 2021). "Inhibition of LAG-3/MHCII interaction with targeted reagents (such as IMP321) was found to activate tumor-related CD8 expression and produce cytokines." (PMID 33717059, 2021). "In the TCGA cohort, we observed similar correlations: M3 tumours showed a higher expression than D3 tumours for LAG3, LSECtin, Galectin-3, HLA-DRalpha, HLA-DQalpha, and HLA-DPalpha (all p = 0.001, Mann–Whitney U test)." (PMID 34503258, 2021). "Although PD-1 therapy is effective in a mouse tumor model, dual blockade of PD-1 and LAG3 shows a synergistic effect." (PMID 34901012, 2021). "In tumors, the density of LAG-3+ tumor-infiltrating lymphocytes was higher in sarcomatoid components than in conventional HCC components." (PMID 34081621, 2021). "Several clinical studies are underway to investigate the utilization of LAG-3 in tumor metastasis diagnosis and prognosis evaluation, and further studies are warranted to explore the efficacy of and tolerance to LAG-3-targeting mAbs." (PMID 34367975, 2021). "In view of this, the evaluation of their ligand expression, such as CEACAM-1 for Tim-3 and LSECtin for Lag-3, on tumor cells is important to prove the inhibition by their axis in the tumor microenvironment." (PMID 33611641, 2021). "PD-1+ and LAG-3+ cell densities were higher in PD-L1+ tumor samples than in PD-L1− tumor samples (PD-1+: 47.3 ± 11.7 vs. 24.0 ± 4.5 cells/mm2; LAG-3+: 54.8 ± 10.7 vs. 29.1 ± 6.7 cells/mm2)." (PMID 34081621, 2021). "The co-expression of LAG-3 with PD-1 on tumor-infiltrating lymphocytes (TILs) has led to extensive research on the synergistic blockade of both receptors to trigger an antitumor immune response." (PMID 34298735, 2021). "In some preclinical studies on different tumor types, LAG-3 monotherapy has largely failed, often in combination with other targets, i.e., the use of dual coblocking will enhance tumor inhibition." (PMID 34447484, 2021).
tumor (continued). "In pre-clinical models, we recently demonstrated that anti-LAG3 immune checkpoint blockade vastly potentiated PI3Kδ-based immunotherapy, enabling successful tumour control in all treated mice." (PMID 33824480, 2021). "Data from the Cancer Genome Atlas (TCGA) shows that LAG-3 expression is highest in DLBCL compared to all other tumor types." (PMID 34068762, 2021). "Among these targets, Tim-3 and Lag-3 show considerably high potential because their co-expression with PD-1 have been reported to dysfunction tumor-specific T cells." (PMID 33611641, 2021). "PD-L1 monotherapy, as well as its combination with LAG-3 blockade, resulted in in-vivo delayed tumor growth and significant survival benefit." (PMID 33466653, 2021). "LAG-3 expression is increased in HCC tumor-infiltrating lymphocytes (TILs) and LAG-3 expression is correlated with impaired T cell effector function." (PMID 34440865, 2021). "In this study, LAG-3 expression on nucleated cells within the tumor and invasive margin was determined using immunohistochemistry." (PMID 33712537, 2021). "In this automated analysis, positively stained immune cells in tumours were distinguished together with nuclei and counted, as illustrated for LAG-3, TIM-3, and TIGIT (respectively)." (PMID 34545095, 2021). "The density of LAG-3+ tumor-infiltrating lymphocytes was lower in peritumoral tissue than in tumor tissue." (PMID 34081621, 2021). "In fact, PD-1/PD-L1 blockade was shown to upregulate LAG-3 or other immune checkpoints as a compensatory mechanism in tumor-bearing mouse models." (PMID 34504192, 2021). "The higher activity of checkpoints, such as TIM3 and LAG3, is also the one of characteristics of the hot tumor." (PMID 34790235, 2021). "LAG3 inhibits the tumor immune microenvironment by accelerating T cell exhaustion and blocking T cell proliferation." (PMID 35111155, 2021). "For combinatorial therapy using anti-PD-1 mAb with anti-Lag-3 mAb or anti-Tim-3 mAb to work effectively, the presence of CTLs in the tumor microenvironment is essential." (PMID 33611641, 2021). "The presence of some activating receptors such as OX40 and ICOS was increased in the surface of CD8 cells in the tumor, whereas the inhibitory receptor LAG3 was reduced in tumor-specific CD8+ T lymphocytes." (PMID 33920699, 2021). "In the last few years, other immune checkpoints have been considered as possible mediators of immune escape by tumor cells; among them, LAG-3, TIM-3 and VISTA have been identified as possible targets in MPM patients." (PMID 34199722, 2021). "Studies using CRISPR-Cas9 mediated gene editing demonstrate that the knockout of PD-1 and LAG3 in CAR-T cells overcome the immunosuppressive nature of the tumor environment, a key factor limiting CAR-T efficacy." (PMID 34068762, 2021). "In ELISpot assay using MKN45, up-regulation of IFN-γ production from CTL clones was observed when CTL clones were reactivated with anti-PD-1 or anti-Lag-3 mAb, or tumor cells treated with anti-PD-L1 mAb." (PMID 33611641, 2021). "In mice, tumor-infiltrating ILC1-like cells transdifferentiated from NK cells downstream of TGF-β signalling expressed higher levels of LAG-3 than NK cells." (PMID 34885076, 2021). "Particularly, highly immunogenic tumors susceptible to immunotherapy like melanoma, microsatellite instable colorectal cancer, or triple-negative breast cancer carry PD-1+/LAG-3+ CD8+ tumor-infiltrating T cells." (PMID 33413541, 2021). "When PD-1 blockade was combined with LAG-3 blockade, a synergistic effect on tumor growth delay was observed." (PMID 33712537, 2021). "As a specific example, LAG-3 DNA methylation correlates with expression of this immune checkpoint molecule in tumor and immune cells, impacting the fate of immune cell infiltrates in clear cell renal cell carcinoma." (PMID 34930302, 2021).
tumor (continued). "T cell deficits that occur during GBM pathogenesis are characterized by increased expression of immune checkpoint molecules (e.g., PD-1, Tim3, and Lag3) that negatively regulate tumor immune responses." (PMID 33232299, 2021). "Currently, there are several clinical trials evaluating the effect of LAG-3 inhibitors in different tumor types." (PMID 34442393, 2021). "We also uncovered that the high-risk cluster exhibited elevated expression levels of PD1, PDL1, CTLA4, LAG3, and TIGIT compared to the low-risk counterpart, supporting the contribution of hypoxia to the tumor immune escape in HCC." (PMID 34917132, 2021). "Specifically, the expression of LAG-3 on tumor infiltrating lymphocytes, natural killer cells, B cells and dendritic cells indicates its involvement in a widespread and complex immune pathways." (PMID 34691076, 2021). "The structure of IMP321 is similar to that of LAG3, with D1-D4 domains to activate monocytes, DCs, and tumor-specific T cell immune responses by competitively binding to MHC-II." (PMID 35111155, 2021). "Hierarchical clustering of the 47 metastatic ccRCC tumour samples based on the normalized LAG-3-, TIM-3-, and TIGIT-positive cell densities identified three groups with distinct IR levels." (PMID 34545095, 2021). "The differential expression of LAG3 in different tumor cells indicates a different patient prognosis." (PMID 35111155, 2021). "According to our recent study, high expression of LAG-3 in tumor tissue indicated an unfavorable prognosis in HCC." (PMID 34691076, 2021). "In the tumour microenvironment, LAG-3 becomes upregulated on Tregs, gathers around tumour sites and exerts immunosuppressive roles that amplify dysfunctional cytotoxic T cells and induction of deficient antitumour immune response." (PMID 33921181, 2021). "Recently, it was reported that FGL1 is a major ligand of LAG3, and genetic ablation or mAbs blocking the FGL1-LAG3 interaction enhanced T cell responses and promoted anti-tumor immunity." (PMID 33968077, 2021). "In this model, tumour control is mediated by targeting LAG-3-expressing NK cells with anti-LAG-3 antibodies." (PMID 33262520, 2021). "By applying therapeutic tumor vaccination, tumor growth is delayed but escape mechanisms evolve, including upregulation of immune-checkpoint molecules (LAG-3, PD-L1)." (PMID 33870463, 2021). "LSECtin, as a member of the DC-SIGN family, is expressed on liver and melanoma cells and can bind LAG-3, thus promoting tumor progression." (PMID 34572263, 2021). "LAG-3 has been identified on various tumor cells, including UCEC, as a critical inducer for the malignancy progression." (PMID 34901000, 2021). "In murine studies, blockade of LAG-3 alone or in combination with anti-PD-1 has been shown to enhance the anti-tumour CTL response and inhibit tumour growth." (PMID 33401460, 2021). ", have shown that in pre-clinical models of MPM, a combination of an anti-PD-1/anti-LAG-3 results in delayed tumor growth and survival benefit." (PMID 33952230, 2021). "Herein, we analysed forty-three ccRCC tumour samples from COHORT 1 comprising the LAG-3 (n = 16), TIM-3 (n = 19), and TIGIT (n = 8) clusters for alterations in 160 cancer-associated genes." (PMID 34545095, 2021). "Immune checkpoints such as CD276 and LAG‐3 were upregulated, and higher M2 macrophage infiltration in tumor tissues." (PMID 33033616, 2020). "Research in mouse xenografts revealed that co-targeting of PD-1 and LAG-3 on TILs can limit tumor growth, which is likely superior to a single inhibitory mechanism." (PMID 33329549, 2020). "We refrained from conducting further subgroup analysis to compare LAG3 methylation in visceral metastases of different tumor sites as the single subgroups included in the TCGA data are too small to allow for valid subgroup analyses." (PMID 32861198, 2020).